IGF1 (insulin like growth factor 1)
Diseases named in the same sentence as IGF1 in open-access papers (continued):
Sharing a sentence is not in itself a finding about the gene and the disease.
depression (continued). "IGF-1 has been described as a potential biomarker for mood disorders and leptin has also been implicated in anxiety and depression related responses; thus, it is possible that leptin and IGF-1 interact in the regulation of central nervous system functions." (PMID 26382238, 2015). "There are several additional growth factors that also have been implicated in neurogenesis, depression, and treatment response, such as insulin-like growth factor-1 (IGF-1), vascular endothelial growth factor (VEGF), and fibroblast growth factor-2 (FGF-2)." (PMID 25477997, 2014). "Depression of the growth hormone – insulin-like growth factor-1 axis was evident at enrollment and associated with inflammatory activation." (PMID 25189855, 2014). "Irrespective of a history of depression, PHQ-9 scores increased across all TBI groups as IGF-1 Z-scores decreased, suggesting that following a TBI, the severity of depression symptoms is more closely associated with IGF-1 levels than with a previous history of depression." (PMID 40697802, 2025). "We hypothesized lower IGF-1 level to be associated with increased symptom severity and incidence of depression and anxiety after TBI." (PMID 40697802, 2025). "Interestingly, an ROC curve analysis including BDNF and IGF-1 offered an excellent diagnostic value for depression (AUC = 0.916, p < 0.0001), which was higher than BDNF or IGF-1 separately." (PMID 40141202, 2025). "The association of IGF-1 with depression could indicate its usefulness as a marker for psychological improvement during the course of treatment of AN, considering its role in neuroplasticity, cognition and mood regulation." (PMID 40284205, 2025). "Elevated IGF-1 levels may increase the risk of developing depression, but seems to also mediate the rapid antidepressant effect of ketamine." (PMID 38091084, 2024). "Additionally, evidence has shown that moderate levels of IGF-1 are associated with a reduced risk of depression." (PMID 38977982, 2024). "We hypothesized that IGF-1 polymorphism is a risk factor for depression in the context of oxidative stress." (PMID 35498133, 2022). "Interestingly, the antidepressant effect of irisin seemed to be principally associated with two neurotrophins (BDNF and IGF-1), whose combined effect on depression reduction has already been reported in rats by i.c.v. irisin injections." (PMID 35886944, 2022). "However, other studies have shown that high values of IGF-1 are associated with higher levels of depression." (PMID 34574400, 2021). "Hence, the role of IGF-1 in the mechanism underlying the therapeutic effect of exercise on depression is inconclusive." (PMID 33154698, 2020). "In line with a potential greater influence of IGF-1 on SNc neurons, we found that behavioral tasks designed to assess anxiety, depression, and anhedonia, usually associated with the mesolimbic pathway that is predominantly regulated by VTA neurons, were not affected in Igf1 cKO mice." (PMID 30808767, 2019). "Increasing (IGF-1) is associated with improved mood, anxiety status and depression." (PMID 31438638, 2019). "Thus, BDNF has been found to be reduced in depression and anxiety disorders in clinical studies, while IGF-1 has been associated with the etiology of depression, particularly in learning and memory deficits, correlating with fatigue, tension and anxiety." (PMID 29108028, 2017). "Accordingly, against this background of study paucity, discordant findings and methodological concerns, we examined the cross-sectional and longitudinal association between IGF-1 and depression symptoms in a large, well-established general population-based study of older adults in England (UK)." (PMID 27648920, 2016). "Notably, a deficiency in IGF-1 can lead to mitochondrial fragmentation, often accompanied by dysfunction, reduced ATP production, and oxidative stress, ultimately mediating the onset of depression through impaired energy metabolism." (PMID 40699781, 2025).
depression (continued). "In lipopolysaccharide (LPS)–induced depression models, ketamine’s antidepressant effects were shown to depend on IGF-1 release in the medial prefrontal cortex." (PMID 41340853, 2025). "Specifically, a one-point increase in the IGF-1 Z-score is associated with a 29.85% decrease in anxiety symptoms on the GAD-7, a 16.30% reduction in depression severity on the PHQ-9, and a 39.23% decrease in post-TBI symptom severity on the RPQ-13." (PMID 40697802, 2025). "PHQ-9 and GAD-9 scores strongly negatively correlated with IGF-1Z-scores in the msTBI group, suggesting a strong correlation between decreasing serum IGF-1 and increasing symptoms of depression and anxiety." (PMID 40697802, 2025). "In this study, we analyzed serum IGF-1 levels, symptom severity, as well as depression and anxiety severity post-TBI." (PMID 40697802, 2025). "Pregnant women with a high serum IGF-1 concentration in the first trimester were less likely to develop postpartum depression than those with a low concentration." (PMID 40277811, 2025). "The aim of this study was to determine associations between IGF-1 levels and post-TBI symptom severity, anxiety, and depression." (PMID 40697802, 2025). "GAD-7 and PHQ-9 scores for the mTBI group were moderately negatively correlated with IGF-1 Z-scores, indicating moderately correlated increase in symptoms of anxiety and depression with decreasing serum IGF-1." (PMID 40697802, 2025). "It is the first study to find that forest bathing increased blood serotonin, oxytocin and IGF-1 in females with depression/depressive tendencies." (PMID 40277811, 2025). "Serum IGF-1 levels were evaluated in relation to the incidence of depression in dwelling elderly people." (PMID 40141202, 2025). "A single correlation between decreased IGF-1 and improved depression in the MBSR+CCT group emerged in the complete-case analysis but did not persist in the per-protocol analysis (≥80% adherence)." (PMID 40283415, 2025). "Another study made in the KORA-age cohort, determined that IGF-1 serum levels were positively correlated with increased depressive symptoms according to the Geriatric Depression Scale (GDS), but just in women." (PMID 40141202, 2025). "It is interesting to find that IGF-1 has also been explored in these contexts, proving the potential link between depression and IGF-1." (PMID 40141202, 2025). "Conversely, an increased incidence of delirium was significantly correlated with the presence of depression and IGF-1 levels in older patients." (PMID 40141202, 2025). "This study reveals the significant inverse relationship between serum IGF-1 levels and the severity of post-injury symptoms, depression, and anxiety in patients with both mTBI and msTBI." (PMID 40697802, 2025). "Specifically, a one-point increase in the IGF-1 Z-score is associated with a 29.85% decrease in anxiety symptoms (GAD-7), a 16.30% reduction in depression severity (PHQ-9), and a 39.23% decrease in post-TBI symptom severity (RPQ-13)." (PMID 40697802, 2025). "It has also been found that insulin-like growth factor 1 (IGF-1) levels are elevated in the serum of patients with major depression." (PMID 38707461, 2024). "To date, the results of studies on IGF-1 levels in patients with depression remain controversial, and few studies have focused on patients with a first episode of clearly diagnosed depression who had never used antidepressants before." (PMID 38919642, 2024). "Other biological mediators related to depression and body composition parameters such as insulin growth factor-1 (IGF-1), tumor necrosis factor alpha (TNF-α), interleukin-8 (IL-8), and matrix metalloproteinase-9 (MMP-9) were also determined." (PMID 38362105, 2024). "According to preclinical results, short-term intervention of central IGF-1 can help reduce depression-like behavior in aged mice, and researchers have also shown that women over 90 years old have lower IGF-1 levels." (PMID 38919642, 2024).
depression (continued). "Serum IGF-1 expression levels were higher in patients with early PD than in patients in the middle and late stages, indicating that serum IGF-1 levels are significantly negatively correlated with anxiety, depression, and cognitive impairment." (PMID 37815899, 2024). "The present study points to a complex relationship between IGF-1 and depression; high and low levels of IGF-1 increased the prevalence of MDD in different phases of investigation, and mid concentrations decreased the probability of incident minor depression." (PMID 38919642, 2024). "After supplementation with blackcurrant anthocyanins (BCA), cGP content increased, and anxiety and depression scores in PD patients decreased, presumably related to the neurotrophic function of IGF-1." (PMID 36383265, 2023). "In a rat model of depression, IGF-1 exerted its antidepressant effects through the PI3K/Akt/Fox3 pathway." (PMID 37569574, 2023). "Serum IGF-1 levels were significantly negatively correlated with anxiety, depression, and cognitive dysfunction; serum EGF levels were significantly negatively correlated with cognitive dysfunction." (PMID 36383265, 2023). "The pathophysiology underlying major depressive disorder (MDD) and schizophrenia is related to endocrine system functions and includes changes in the blood levels of cortisol and insulin-like growth factor 1 (IGF-1)." (PMID 36670169, 2023). "On the contrary, in the last few decades, IGF-1 has received far more attention than IGF-2 in the context of depression." (PMID 37894932, 2023). "Among the PD patients, serum IGF-1 levels were lower in the anxiety subgroup, depression subgroup, and cognitive dysfunction subgroup than in the subgroups without anxiety (143.66 ± 35.47 mmol/L vs." (PMID 36383265, 2023). "BDNF-mediated signaling along with vascular endothelial growth factor (VEGF) and insulin-like growth factor 1 (IGF-1) subsequently give rise to the repair of neuro-structural abnormalities in patients with depressive disorders." (PMID 37242525, 2023). "Several proteins, among them Insulin-like Growth Factor-1 (IGF-1), Metalloproteinase type 1 (TIMP-1), and Vascular Cell Adhesion Molecule type 1 (VCAM-1) were reported to mediate association between dementia and depression." (PMID 35326481, 2022). "Other neurotrophic/growth factors linked to depression include the vascular endothelial growth factor (VEGF), the fibroblast growth factor 2 (FGF2), and the insulin-like growth factor 1 (IGF-1)." (PMID 35056845, 2022). "Previous studies have shown that systemic and central administration of IGF-1 produces sustained (at least 6 days) antidepressant-like behavioral effects in various rodent models of depression." (PMID 35577782, 2022). "Consistent with this, a decrease in IGF-1 signaling has been related to neurodegeneration, depressive disorders, and other brain diseases." (PMID 35401920, 2022). "Few studies attempting to determine the role of IGF-1 in the diagnosis and treatment of depression have been published." (PMID 34362162, 2021). "According to a recent umbrella meta-analysis, insulin-like growth factor-1 (IGF-1) is another growth factor which is significantly elevated in depression." (PMID 33255237, 2020). "IGF-1 regulates cell growth, and has been implemented in the ageing process but also in psychosocial outcomes such as depression." (PMID 31491488, 2019). "In line with this notion, when administrated chronically, a peripheral injection of IGF-1 in a mouse model of depression was shown to induce antidepressant-like behaviors, comparable to commonly used antidepressants." (PMID 29961124, 2018). "Immune effects of IGF-1 are also attracting attention, given the importance of neuroinflammation in the pathogenesis of depression and cognitive dysfunction." (PMID 29093741, 2017). "Reduced expression of IGF-1 along with the decrease in serotonin has been found in male rats with depression-like traits due to social isolation." (PMID 29093741, 2017).
depression (continued). "Despite the presence of harmonized experimental data on the decreased IGF-1 levels in brain in depression and cognitive impairment, there are discrepancies in the estimation of the peripheral IGF-1 concentrations in patients suffering from MDD." (PMID 29093741, 2017). "Consistent with this, a decrease in IGF-1 signaling has been related with neurodegeneration, depressive disorders and other brain diseases, in which IGF-1 has been suggested as a possible therapy." (PMID 29163145, 2017). "Although VEGF and IGF-1 are thought to be important factors in pathophysiology of depression because of their neurotrophic effects, unfortunately, no different neurotrophic factor was observed in PSD and Non-PSD group." (PMID 27527872, 2016). "The aim of the current study was to conduct a thorough meta-analysis of changes in peripheral IGF-1 levels in patients with major depressive disorder (MDD) or bipolar disorder (BD)." (PMID 26825882, 2016). "In contrast, the experimental bulbectomy, thus lowering the IGF-1 level, has been established as a rodent model of depression." (PMID 26610812, 2016). "In these new analyses, we still found evidence for increased odds of depression symptoms among those with very low and very high IGF-1." (PMID 27648920, 2016). "To date, there have been no papers showing the impact of chronic antidepressant treatment on the IGF-1 network in the olfactory bulb (OB) in an animal model of depression." (PMID 26610812, 2016). "In the light of the discovery of alterations in IGF-1 levels in depression-like states, its antidepressant-like activity was discovered in various animal models of depression." (PMID 27527872, 2016). "We did not investigate the temporal expression of GFAP in our samples, but we found a report of gradual reduction in GFAP expression following IGF-1 treatment in a rodent model of depression." (PMID 27272754, 2016). "Our results partially accord with the two population studies on IGF-1 and depression of which we are aware." (PMID 27648920, 2016). "Adjustment for an array of covariates had little impact on this pattern of association, although taking into account all covariates simultaneously led to some flattening of the IGF-1–depression relationship." (PMID 27648920, 2016). "Adult rats exposed prenatally to stressful stimuli displayed not only depression-like behavior but also decreased IGF-1 expression, dysregulation in the IGFBP network, and diminished mRNA expression, as well as IGF-1R phosphorylation, in the OB." (PMID 26610812, 2016). "Microglia in this animal model of depression are impaired in their ability to produce the neurotrophic factor IGF-1." (PMID 25814933, 2015). "Interrupting monotony through introduction of novel objects during isolation to ameliorates anxiety and depression like traits and preserves neuronal architecture through an IGF-1-serotonin mediated mechanism." (PMID 25880744, 2015). "In pediatric IBD, linear growth impairment correlates with cytokine-mediated depression of the growth hormone – IGF-1 axis, and a similar effect was evident among participants in this trial." (PMID 25189855, 2014). "Among the mechanisms proposed there are: reduced physical activity, sleep disturbances, depression, dysfunction of thyroid gland and dysfunction of the GH/IGF-1 axis." (PMID 24618795, 2014). "Abnormal IGF-1 levels have also been reported in several psychiatric disorders like schizophrenia and major depression." (PMID 25386163, 2014). "Curiously, in older participants (>50 years), higher IGF-1 levels were found to be associated with lower levels of loneliness, independent of age, medical history, and depression." (PMID 40141202, 2025). "The finding that forest bathing increases the level of IGF-1 in patients with depression is new." (PMID 40277811, 2025).
depression (continued). "IGF-1 was lower in people with AN compared with HCs but higher in participants with AN who had a history of depression, indicating that IGF-1 may play a role in affective comorbidity in people with AN." (PMID 40284205, 2025). "Thus, we investigated the impact of forest bathing on IGF-1 and found that forest bathing significantly increased blood IGF-1 compared with city walking, indicating a beneficial effect of forest bathing on IGF-1 in patients with depression." (PMID 40277811, 2025). "Posteriorly, the studies of Levada and Troyan explored IGF-1 as a neurotrophic factor in which reduced expression could impair neuroplasticity in depression." (PMID 40141202, 2025). "Finally, it was found that IGF-1 concentrations were higher in people with AN or recAN that reported a history of depression." (PMID 40284205, 2025). "It was not until 2014 when the first population-based study was made relating IGF-1 and depression." (PMID 40141202, 2025). "Although this association is controversial, recent meta-analytical evidence showed an increase in IGF-1 in patients with depression and that it might be utilised as a trade marker for depression." (PMID 40284205, 2025). "IGF-1 is additionally correlated with hypoxia and long COVID symptoms, including depression." (PMID 40048451, 2025). "Third, as is the case with Ad treatment, IGF-1 may increase in early stages of depression and then decrease in later stages, since these patients would have been exposed to Ads more frequently." (PMID 40141202, 2025). "Our findings suggest that decreased circulating IGF-1 is associated with increased RPQ-13, GAD-7, and PHQ-9 scores in both mTBI and msTBI, reflecting increased post-injury symptom severity and higher rates of depression and anxiety." (PMID 40697802, 2025). "However, there has yet to be any research on the impacts of forest bathing on blood oxytocin and IGF-1 levels in patients with depression." (PMID 40277811, 2025). "This suggests that the CREB/PGC-1α signaling pathway may be an important molecular mechanism through which IGF-1 improves depression by regulating mitochondrial function." (PMID 40699781, 2025). "Low serum IGF-1 levels increase vulnerability to stress, and cause depression, whereas obese or depressed individuals show either high bioactive IGF-1 or high serum IGF-1 levels, respectively, hinting to a status of IGF-1 resistance." (PMID 41155299, 2025). "In addition, IGF-1 reduces depressive disorders and memory impairment, and improves cognitive functions." (PMID 40801621, 2025). "Therefore, this study investigated first-episode and drug-naïve patients with depression to supplement the current evidence around IGF-1 levels in depressive disorders." (PMID 38919642, 2024). "Another hormone that might play an important role in the context of depression and a dysregulated metabolism is Insulin-like Growth Factor—1 (IGF-1)." (PMID 38091084, 2024). "In the current study, the age distribution of the sample was not adequately differentiated due to sample size limitations, although a study on IGF-1 concentration and depression degree in different age groups may help explain this phenomenon." (PMID 38919642, 2024). "In addition to the possible role of IGF-1 dysregulation in depression, IGF-1 modulation within the prefrontal cortex plays a role in the mechanism of action of fluoxetine." (PMID 37242525, 2023). "It should be noted that the influence of fibrinogen and some coagulation factors cannot be excluded in plasma unlike in serum samples, as well as that sample type was also a source of heterogeneity in the meta‐analysis of peripheral IGF‐1 levels in bipolar disorder and major depressive disorder." (PMID 36448977, 2023). "Meta‐analysis of peripheral IGF‐1 levels in bipolar disorder and major depressive disorder also noted that regional differences may be a potential source of heterogeneity, which could be related to different geographical and cultural diet habits." (PMID 36448977, 2023).